TRGC2 (T cell receptor gamma constant 2)
Description:
Constant region of T cell receptor (TR) gamma chain that participates in the antigen recognition. Gamma-delta TRs recognize a variety of self and foreign non-peptide antigens frequently expressed at the epithelial boundaries between the host and external environment, including endogenous lipids presented by MH-like protein CD1D and phosphoantigens presented by butyrophilin-like molecule BTN3A1. Upon antigen recognition induces rapid, innate-like immune responses involved in pathogen clearance and tissue repair. Binding of gamma-delta TR complex to antigen triggers phosphorylation of immunoreceptor tyrosine-based activation motifs (ITAMs) in the CD3 chains by the LCK and FYN kinases, allowing the recruitment, phosphorylation, and activation of ZAP70 that facilitates phosphorylation of the scaffolding proteins LCP2 and LAT. This lead to the formation of a supramolecular signalosome that recruits the phospholipase PLCG1, resulting in calcium mobilization and ERK activation, ultimately leading to T cell expansion and differentiation into effector cells. Gamma-delta TRs are produced through somatic rearrangement of a limited repertoire of variable (V), diversity (D), and joining (J) genes. The potential diversity of gamma-delta TRs is conferred by the unique ability to rearrange (D) genes in tandem and to utilize all three reading frames. The combinatorial diversity is considerably increased by the sequence exonuclease trimming and random nucleotide (N) region additions which occur during the V-(D)-J rearrangements.
Synonyms: TCRGC2; TRGC2(2X); TRGC2(3X)
Gene: T-cell receptor constant (C) gene on chromosome 7 (38,239,580 to 38,249,572, reverse strand). Ensembl gene ENSG00000227191.
Subcellular location: Cell membrane
Genetic constraint (gnomAD): Missense variants: 125 observed, 120.02 expected, observed/expected ratio (o/e) 1.04, 90% interval 0.9 to 1.21. Synonymous variants: 43 observed, 41.83 expected, observed/expected ratio (o/e) 1.03, 90% interval 0.8 to 1.33.
Homologues: Paralogues in human: TRGC1 (89% identical), TRGV1 (0% identical), TRGV2 (0% identical), TRGV3 (0% identical), TRGV4 (0% identical), TRGV5 (0% identical), TRGV8 (0% identical).
Diseases named in the same sentence as TRGC2 in open-access papers:
TRGC2 is named in the same sentence as 4 diseases in open-access papers, as found by Europe PMC text mining. Sharing a sentence is not in itself a finding about the gene and the disease. The quoted sentences say what the papers report.
leukoplakia (1 paper, 2024). A white patch or plaque on a mucous membrane that cannot be characterized clinically or pathologically as any other disease. "During the progression from leukoplakia to HNSCC, we found several prognostic cell subgroups, such as AURKB + epithelial cells, SFRP1 + fibroblasts, SLC7A8 + macrophages, FCER1A + CD1C + dendritic cells, and TRGC2 + NK/T cells." (PMID 38582791, 2024).
myositis (1 paper, 2018). "We found that PI4KAP1 had a higher expression in CD4+ T cells of HLA-DRB1*03-positive myositis and that TRGC2, CTSW, HPCAL4, ZNF683, and GOLGA8B had a higher expression in CD4+ T cells of HLA-DRB1*03-negative myositis patients." (PMID 30157932, 2018). "PI4KAP1 was found to have a higher expression in CD4+ T cells of HLA-DRB1*03-positive patients with myositis, and TRGC2, CTSW, HPCAL4, ZNF683, and GOLGA8B were found to have a higher expression in CD4+ T cells of HLA-DRB1*03-negative patients with myositis." (PMID 30157932, 2018).
infection (2 papers, 2022 to 2023). The state of being infected such as from the introduction of a foreign agent such as serum, vaccine, antigenic substance or organism. "The CeD-dominated cluster C1 differentially expressed genes including TRGC2, IKZF2, GPR18, TRDC and KLHL42 that are associated with ‘infection’ related response pathways including ‘NOD-like receptor signaling pathway’ in gene ontology analysis." (PMID 35995787, 2022).
TRGC2 also shares sentences with these, for which no sentence is quoted: tumor (3 papers).